MIR193B (microRNA 193b)
Synonyms: hsa-mir-193b; MIRN193B; mir-193b
Gene: MicroRNA gene on chromosome 16 (14,303,967 to 14,304,049, forward strand). Ensembl gene ENSG00000207639.
Gene Ontology:
Biological process: miRNA-mediated post-transcriptional gene silencing
Homologues: Orthologues: chimpanzee ptr-mir-193b (100% identical), macaque mml-mir-193b (100% identical), pig MIR193B (98% identical), rat Mir193b (95% identical), guinea pig MIR193B (92% identical), mouse Mir193b (90% identical), rabbit MIR193B (90% identical), tropical clawed frog xtr-mir-193 (81% identical), zebrafish mir193b (76% identical), dog MIR193B (69% identical), Drosophila melanogaster mir-193 (54% identical). Paralogues in human: MIR193A (60% identical).
Diseases named in the same sentence as MIR193B in open-access papers:
MIR193B is named in the same sentence as 2 diseases in open-access papers, as found by Europe PMC text mining. Sharing a sentence is not in itself a finding about the gene and the disease. The quoted sentences say what the papers report.
meningioma (1 paper, 2023). A generally slow growing tumor attached to the dura mater. "Hypermethylation of MIR193B is related to downregulation of hsa-miR-193b-3p and hsa-miR-193b-5p in meningiomas." (PMID 37686289, 2023). "The DNA methylation level of MIR193B is higher in atypical WHO GII as compared to benign WHO GI tumors, which corresponds with higher hsa-miR-193b-3p expression in GII than GI meningiomas." (PMID 37686289, 2023).
MIR193B also shares sentences with these, for which no sentence is quoted: GI tumors (1 paper).